LINC01612 (long independently transcribed non-coding RNA 1612)
Synonyms: RP11-789C1.1; TCONS_00008319; linc-GALNTL6-4
Gene: Long non-coding RNA gene on chromosome 4 (170,226,496 to 170,284,885, forward strand). Ensembl gene ENSG00000250266.
Diseases named in the same sentence as LINC01612 in open-access papers:
LINC01612 is named in the same sentence as 9 diseases in open-access papers, as found by Europe PMC text mining. Sharing a sentence is not in itself a finding about the gene and the disease. The quoted sentences say what the papers report.
hepatoma (3 papers, 2022 to 2025). "In order to explore the specific mechanism of Linc01612 inhibiting the biological function of hepatocellular carcinoma, we performed transcriptome sequencing in Linc01612 overexpressed HCC cells." (PMID 35541917, 2022). "Linc01612 mainly localizes in the cytoplasm and functions as a tumor suppressor by repressing the growth and metastasis of hepatoma cells in vitro and in vivo." (PMID 35541917, 2022). "We examined Linc01612 expression levels in different hepatoma cell lines by RT-qPCR." (PMID 35541917, 2022). "Finally, we indicated that Linc01612 could interact with miR-494 to upregulate the expression of ATF3 in hepatocellular carcinoma." (PMID 35541917, 2022).
cholangiocarcinoma (1 paper, 2022). A carcinoma that arises from the intrahepatic biliary tree (intrahepatic cholangiocarcinoma) or from the junction, or adjacent to the junction, of the right and left hepatic ducts (hilar cholangiocarcinoma). "Further, the expression of Linc01612 was analyzed in 8 pairs of cholangiocarcinoma samples and showed similar results." (PMID 35541917, 2022).
gastric cancer (1 paper, 2025). A primary or metastatic malignant neoplasm involving the stomach. "Moreover, LINC01612 inhibits gastric cancer cell proliferation, induces apoptosis by binding to ATR and suppressing CHK1 phosphorylation, and enhances oxaliplatin sensitivity." (PMID 41135528, 2025).
cancer (4 papers, 2019 to 2025). A tumor composed of atypical neoplastic, often pleomorphic cells that invade other tissues. "Seven genes were expressed in non-cancerous tissues only, including LINC01612 (TSG), FAM3D (inflammation), HCN1, and CNBD1 (mutation in cancer) and three other genes." (PMID 37509325, 2023).
tumor (4 papers, 2022 to 2025). "In summary, our findings suggest that Linc01612 functions as a tumor suppressor in vitro and in vivo." (PMID 35541917, 2022). "In this study, we discovered that Linc01612 is significantly down-regulated in HCC tissues than in non-tumor tissues and correlated with poor prognosis." (PMID 35541917, 2022). "Compared to the negative control group, the tumor size and tumor volume were significantly decreased in Linc01612 overexpression group." (PMID 35541917, 2022). "Moreover, mRNA expressions of CA14, RPE65, IGSF1, SLC18 A2 and CPNE6 were significantly lower in PCa samples compared to benign samples, while HJURP, COMP, KRTAP5-1, VGF, SSTR1, LINC01612, NAALADL2-AS2, AMH and ARHGDIG were elevated in tumor samples (p < 0.05)." (PMID 40592939, 2025). "Sixteen nearby genes showed higher expression in non-cancerous tissues, including seven with almost no expression in tumor (HCN1, SLC22A2, FAM3D, LRFN5, LINC01612, LINC02512, and CNBD1)." (PMID 37509325, 2023).
LINC01612 also shares sentences with these, for which no sentence is quoted: adenoma (1 paper); dysplasia (1); hypertriglyceridemia (1); Obesity (1).